TRPC3 (transient receptor potential cation channel subfamily C member 3)
Diseases named in the same sentence as TRPC3 in open-access papers (continued):
Sharing a sentence is not in itself a finding about the gene and the disease.
Ataxia (continued). "Thus, the disruption of the TRPC3 signaling pathway might be a common pathological mechanism underlying cerebellar ataxia in mouse and human." (PMID 25908616, 2015). "CAGC (Centralized Ataxia Genomics Core), started in 2020, currently hosts > 850 ataxia datasets and has already contributed to the discovery of TRPC3 as a novel ataxia gene." (PMID 36869969, 2024). "Calcium channels, including Cav2.1, Cav3.1, TRPC3, and IP3R1, and calcium pumps, including PMCA2 and PMCA3, have been implicated in cerebellar ataxia in both humans and mice." (PMID 37374132, 2023). "Perturbed TRPC3 signaling is likely to be a common pathological mechanisms in other genetic forms of cerebellar ataxia." (PMID 31892274, 2019). "Abnormal TRPC3 signaling is likely to be a common pathological mechanisms in different subtypes of ataxia, suggesting a pathological role for PKCγ beyond SCA14." (PMID 30249303, 2018). "The gain-of-function Mwk mouse has provided novel insights into the function of TRPC3 in the normally developing cerebellum as well as in cerebellar ataxia." (PMID 24797279, 2014). "Thus, TRPC3 proteins play an essential role in both progression and continuity of dendritic and Purkinje cells intervening in cerebellar ataxia." (PMID 37332910, 2023). "The findings of this study may be useful in identifying the mechanistic basis of TRPC3 signaling and possible targeting opportunities of this channel protein in hereditary forms of human cerebellar ataxia." (PMID 35265671, 2022). "Abnormal Ca++ signaling due to enhanced TrpC3 activity is expected to affect type II UBC electrical activity and thus, likely may be an early contributor to ataxia that precedes the loss of type II UBCs in this mouse." (PMID 32034189, 2020). "Collectively, these findings point to a crucial role of TRPC3 signaling in hereditary forms of human cerebellar ataxia, making the TRPC3 gene a promising candidate for screening ataxic patients with unknown genetic etiology." (PMID 31892274, 2019). "Although these studies contradict one another, they still suggest that TRPC3 could have a pivotal role in Purkinje neurons, and future studies are needed to confirm the role of TRPC3 in ataxia." (PMID 24852263, 2014). "Hopefully, more selective and potent pharmacological modulators of TRPC3 will be developed in the near future that could hold great promise as therapeutic agents for cerebellar ataxia." (PMID 24797279, 2014). "Given the importance of the TRPC3 pathway in cerebellar ataxia, the Mwk mouse promises to be a valuable model to test novel compounds that might be beneficial in human cerebellar ataxia." (PMID 24797279, 2014). "Consequently, TRPC3 activity deregulation might induce structural alterations during the progress of cerebellar ataxia by modulating dendrite development." (PMID 33240883, 2020). "So far, candidate screening of the TRPC3 gene did not identify potential mutations in patients with sporadic late-onset cerebellar or episodic ataxia, suggesting that TRPC3 mutations are unlikely to be a common cause of cerebellar ataxia." (PMID 24797279, 2014). "The TRPC3 channel itself might be an attractive target to modulate in cerebellar ataxia." (PMID 24797279, 2014). "However, TRPC3 mutations might still contribute to cerebellar ataxia in specific subtypes of the disease that have not been screened yet." (PMID 24797279, 2014). "In contrast, no dendritic phenotype and a milder form of ataxia have been observed in the Trpc3 knockout mice." (PMID 25908616, 2015).
breast carcinoma (17 papers, 2009 to 2025). "There are few studies on TRPC channels and breast cancer, but those that have been reported have targeted TRPC1 and TRPC3 as channels associated with breast cancer proliferation." (PMID 40078961, 2025). "In the highly metastatic breast cancer cell line MDA-MB-231 the predominant TRPC channels expressed were TRPC3 and TRPC6 (of longer splice form variants)." (PMID 19689790, 2009). "In breast cancer biopsy tissues, TRPC3 and TRPC6 proteins (determined by Western blotting) were upregulated compared to normal breast tissue." (PMID 37240443, 2023). "It is conceivable that the observed proliferative effect arises through the transfer and incorporation of functional TRPC3 channels into the membrane of recipient cells—as reported for the EV‐mediated transfer of TRPC5 from chemoresistant breast cancer cells." (PMID 38938673, 2023). "As one of the biomarkers of breast cancer development and migration, TRPC3 represents a potential target for a new class of anticancer drugs." (PMID 35573736, 2022). "Polyunsaturated fatty acids (PUFA) and TRPC3 antagonists continuously inhibit the proliferation and migration of breast cancer cells, but the mechanism is still unclear." (PMID 35573736, 2022). "Canonical TRP isoform 3 (TRPC3) channel was reported to be upregulated in breast cancer biopsy tissues when compared to normal breast tissues." (PMID 31003514, 2019). "Canonical transient receptor potential isoform 3 (TRPC3) was previously shown to be upregulated in breast cancer biopsy tissues when compared to normal breast tissues." (PMID 31003514, 2019). "A previous study has reported the abnormal upregulation of TRPC3 and TRPC6 in breast cancer tissues from patients; the differential expression of TRPC3 in MCF-7 and MDA-MB-231 has attracted our attention." (PMID 31003514, 2019). "The data suggest a possible role for TRPC3-mediated Ca2+ entry in breast cancer cell migration although a direct link is still missing." (PMID 24204345, 2013). "Exogenous PUFA as well as a TRPC3 antagonist consistently attenuated breast cancer cell proliferation and migration, suggesting a mechanism in which PUFA restrains the breast cancer partly via its inhibition of TRPC channels." (PMID 22692672, 2012). "In this study, we found the functional expression of TRPC3 in human MCF-7 breast cancer cell-mediated Ca2+ entry." (PMID 22692672, 2012). "Inconsistent to previous studies, we found that TRPC3 in MCF-7 breast cancer cells are activated by DAG as well as by store depletion." (PMID 22692672, 2012). "PUFAs as well as the TRPC3 antagonist attenuated breast cancer cell proliferation and migration, suggesting a mechanism in which PUFAs restrain breast cancer via inhibition of TRPC channels." (PMID 22692672, 2012). "TRPC3 has previously been reported to be upregulated in breast cancer biopsy." (PMID 39436410, 2025). "However recently a functional expression of TRPC3 has been described in MCF-7 breast cancer cell line." (PMID 24204345, 2013). "Additionally, our results also suggest that TRPC3 appears as a new mediator of breast cancer cell migration/invasion and represents a potential target for a new class of anticancer agent." (PMID 22692672, 2012). "In this study, we found that TRPC3 channels were highly expressed in MCF-7 breast cancer cells." (PMID 22692672, 2012). "Thus, TRPC3 appears as a new mediator of breast cancer cell migration/invasion and represents a potential target for a new class of anticancer agents." (PMID 22692672, 2012). "However, the biological role of TRPC3 in breast cancer still remains to be elucidated." (PMID 31003514, 2019). "Additionally TRPC3 appeared to be significantly up regulated in breast cancer tissues." (PMID 19689790, 2009).
breast carcinoma (continued). "For example, in triple-negative aldehyde dehydrogenase-positive (ALDH+) breast cancer cells, LPA/LPAR3 induces Ca2+ signalling through the transient receptor potential cation channel subfamily C member 3 (TRPC3) channel to induce cancer stem cell populations." (PMID 38607068, 2024). "TRPC3 expression correlates with the differentiation grade of non-small cell lung cancer, and abnormal upregulation of TRPC3 and TRPC6 has been reported in breast cancer tissues." (PMID 35216080, 2022). "TRPC channels, including TRPC3, TRPC5, and TRPC6, are typical oncogenic proteins that can be used to diagnose breast cancer." (PMID 33806911, 2021). "In breast cancer biopsy tissues, TRPC3 and TRPC6 were the predominant TRPC genes expressed with TRPC3 and TRPC6 being significantly up regulated compared to normal breast tissue." (PMID 19689790, 2009). "Protein expression of TRPC3 and TRPC6 in breast cancer cell lines appeared to be consistent with the PCR results." (PMID 19689790, 2009). "Our data provides strong evidence that TRPC3 and TRPC6 form heteromutimeric channels in breast cancer epithelial cell line MDA-MB-231, which is consistent with previous reports of TRPC3/6 expression." (PMID 19689790, 2009). "In the lowly metastatic breast cancer cell line MCF-7, TRPC6 was the chief TRPC gene expressed while in the highly metastatic breast cancer cell line MDA-MB-231 both TRPC3 and TRPC6 were the predominant TRPC genes expressed." (PMID 19689790, 2009). "Canonical transient receptor potential isoform 3 (TRPC3), a calcium-permeable non-selective cation channel, has been reported to be upregulated in breast cancer biopsy tissues and a modulator of cancer cell migration." (PMID 39436410, 2025). "Canonical transient receptor potential isoform 3 (TRPC3), a calcium-permeable non-selective cation channel, has been reported to be upregulated in breast cancers and a modulator of cell migration." (PMID 39436410, 2025). "ORAI but not TRPC3 inhibition reduces NNAT-mediated elevation in intracellular Ca2+ concentration in breast cancer cells." (PMID 37400769, 2023). "Furthermore, TRPC3, as well as TRPC6, are up-regulated in breast cancer biopsies and the breast cancer cell lines MCF7 and MDA-MB-231 cells." (PMID 30223530, 2018). "Moreover, several isoforms of TRPC channels, dependent on the cell type, have been implicated in the CaSR activation-induced Ca2+ entry, such as TRPC3 in salivary ductal cells, TRPC1 in MCF-7 breast cancer cells and keratinocytes, and TRPC6 in aortic smooth muscle cells and cardiac myocytes." (PMID 24905090, 2014). "TRPC6 is more highly expressed than other TRPC channels in human breast cancer MCF-7/MDA-MB-231 cell lines (regardless of breast cancer subtypes) and tissues, but TRPC3 is highly expressed only in the estrogen receptor-negative MDA-MB-231 cells and tissues." (PMID 33806911, 2021).
Hypertension (16 papers, 2012 to 2026). The presence of chronic increased pressure in the systemic arterial system. "Understanding the molecular interplay between IP3Rs and TRPC3 channels offers new insight into the dysregulated Ca2+ signaling underlying hypertension." (PMID 42068376, 2026). "The TRPC3-mediated profibrotic effects are linked to cardiac disease conditions such as atrial fibrillation, hypertension, and pressure overload, where the disease conditions directly or indirectly upregulate the expression of TRPC3 or activate the channels." (PMID 36277180, 2022). "To date, no study has investigated the fibrotic response of atrial fibroblast TRPC3 underlying aging and hypertension." (PMID 31871548, 2019). "Since TRPC3/6 channels were implicated in the pathogenesis of hypertension and hypertrophy, GSK255B and GSK503A were tested in animal models of cardiac hypertrophy and remodeling." (PMID 30037143, 2018). "We conclude that increased monocyte migration in patients with essential hypertension is associated with increased TRPC3 channels." (PMID 22438881, 2012). "Both, experiments using the inhibitor 2-APB, as well as specific TRPC3 knockdown using the siRNA technique supported the notion that increased monocyte migration in patients with essential hypertension is associated with increased TRPC3 channels." (PMID 22438881, 2012). "Several evidences support the notion that increased TRPC3 is associated with increased migration of monocytes from patients with essential hypertension." (PMID 22438881, 2012). "Moreover, elevated TRPC3 messenger RNA (mRNA) levels in patients with hypertension were associated with increased salt intake and systolic blood pressure but, its specific mechanism needs further investigation." (PMID 35303866, 2022). "TRPC3 upregulation was also observed in the mesenteric arteries and in aortic tissue of SHRs, where it was associated with exacerbated vasoconstrictions to ET-1 and angiotensin II during hypertension." (PMID 32854408, 2020). "In the present study we tested the hypothesis that increased TRPC3 channel expression causes increased migration of monocytes from patients with essential hypertension." (PMID 22438881, 2012). "TRPC has been reported to increase in models of hypertension, especially a higher TRPC3 and change in TRPC 3/6 proportions in essential in hypertension, which is associated with depolarization of vascular smooth muscle cells." (PMID 35303866, 2022). "Numerous observations associate altered expression of TRPC3 and TRPC6 channels with hypertension in animal models." (PMID 36213221, 2022). "The authors proposed that TRPC3 overexpression in hypertension led to a greater Ca2+ and Na+ influx, depolarization and consequent activation of VDCCs, which enhanced carotid artery contractility." (PMID 32854408, 2020). "Upregulation of TRPC3 induces in cerebrovascular remodeling during hypertension via transactivation of epidermal growth factor receptor- (EGFR-) dependent signaling pathways." (PMID 31871548, 2019). "The aim of this study is to elucidate the mechanism of TRPC3 upregulation-induced fibrosis in aging and hypertension." (PMID 31871548, 2019). "Some studies showed that TRPC3 was increased in vasculature and peripheral blood monocytes in hypertension." (PMID 31871548, 2019). "It means that aging, the same as hypertension, induced upregulation of TRPC3 accompanied with excessive deposition of extracellular matrix." (PMID 31871548, 2019). "An increase in the molecular coupling between inositol 1,4,5-trisphosphate receptor (IP3R) and TRPC3 augments endothelin-1- (ET-1-) induced vasoconstriction during hypertension." (PMID 31871548, 2019). "Researchers also found that upregulation of TPRC3 enhances EGFR transactivation, which is involved in hypertension-induced cerebrovascular remodeling by the signaling pathway TRPC3/ADAM17." (PMID 31871548, 2019).
Hypertension (continued). "Our studies demonstrated that atrial TRPC3 expression was upregulated during aging and hypertension, which was accompanied with the enhancement of fibrotic markers." (PMID 31871548, 2019). "The data indicated that the upregulation of TRPC3 was accompanied with the upregulation of a fibrotic biomarker in aging and hypertension." (PMID 31871548, 2019). "Earlier studies from our group and other groups indicated that increased TRPC3 protein expression is a common finding both in patients with essential hypertension and in animal models of hypertension." (PMID 22438881, 2012). "An increased transient receptor potential canonical type 3 (TRPC3) protein expression has been observed both in patients with essential hypertension and in animal models of hypertension." (PMID 22438881, 2012). "In patients with hypertension an increased TRPC3 expression has been reported in several tissues including vascular smooth muscle cells and peripheral blood monocytes." (PMID 22438881, 2012). "Increased transient receptor potential canonical type 3 (TRPC3) channels have been observed in patients with essential hypertension." (PMID 22438881, 2012). "We found an increased TRPC3 protein expression in monocytes from patients with essential hypertension compared to normotensive control subjects (2.34±0.08 vs. 1.20±0.10; p<0.01)." (PMID 22438881, 2012). "After siRNA knockdown of TRPC3 the fMLP-induced migration was similar in monocytes from patients with essential hypertension and normotensive control subjects." (PMID 22438881, 2012). "We treated monocytes from normotensive control subjects and patients with essential hypertension with small interfering RNA for knockdown of TRPC3 or scrambled siRNA for control." (PMID 22438881, 2012). "In humans, TRPC3 was found to be upregulated in the kidneys of patients with hypertension." (PMID 38791624, 2024). "Indeed, compensatory increases in TRPC3 can lead to an increase in contractility of vascular smooth muscle and hypertension in TRPC6 knockout mice, although the extent to which this occurs depends on genetic background." (PMID 36421724, 2022). "Previous research showed that TRPC3 transcription is closely related to systolic blood pressure ascribed to pro-inflammatory cytokines interleukin-1β (IL-1β) and tumor necrosis factor-α in essential hypertension." (PMID 35303866, 2022). "Meanwhile, TRPC3 upregulation was found in eight-week SHRs without carotid arterial remodeling, but not in 18-week SHRs with arterial remodeling, indicating that TRPC3 may be important for hypertension development." (PMID 32854408, 2020). "Indeed, TRPC3 KO mice showed less severe hypertension through reduction of angiotensin II-induced mitochondrial ROS production, a finding that was validated using Pyr3 inhibitor." (PMID 32872338, 2020). "Interestingly, the upregulation of TRPC3 was also detected in monocytes from SHRs and from patients with essential hypertension." (PMID 32854408, 2020). "TRPC3 may be a potential therapeutic target under the pathophysiology states such as aging and hypertension." (PMID 31871548, 2019). "Additionally, excessive migration of monocytes in essential hypertension is related to upregulation of TRPC3." (PMID 31871548, 2019). "Moreover, TRPC3 channels are found to be involved in the development of hypertension and its related complications." (PMID 30320134, 2018). "The accumulated evidence suggests that TRPC3 channels may play an important role in agonist-induced contraction and cardiovascular disease, especially hypertension." (PMID 25310225, 2014). "Total TRPC3 channel protein expression was also increased in patients with hypertension." (PMID 22438881, 2012). "The present study extended these observations, showing that the increased TRPC3 protein expression may play an important role for increased activation of monocytes in patients with essential hypertension." (PMID 22438881, 2012).
Hypertension (continued). "Hence, upregulation of TRPC3 in aging and hypertension is involved in an atrial fibrosis process." (PMID 31871548, 2019). "TRPC3 may be a potential therapeutic target for preventing fibrosis in aging and hypertension." (PMID 31871548, 2019). "The studies conducted on these channels indicated that TRPM4, TRPC1, TRPC3, and TRPC6 channels play an important role in the creation and progression of hypertrophy and hypertension." (PMID 32641948, 2019). "Additionally, high levels of TRPC3 protein are expressed in spontaneously hypertensive rats (SHR), as well as in patients with hypertension, and upregulated TRPC3 increased the Ca2+ influx in SHRs compared with normotensive Wistar-Kyoto rats (WKY)." (PMID 25310225, 2014). "However, up to date, it is not clear whether TRPC3 upregulation promotes atrial fibrosis related to aging process or hypertension." (PMID 31871548, 2019).